IL1B (interleukin 1 beta)
Diseases named in the same sentence as IL1B in open-access papers (continued):
Sharing a sentence is not in itself a finding about the gene and the disease.
atherosclerosis (continued). "This supports the use of IL-1β inhibitors as a possible treatment for atherosclerosis." (PMID 40283183, 2025). "To evaluate the effect of sodium nitrate on atherosclerosis, we detected inflammatory cytokine expression in mouse aortas by using QPCR and found that the expression levels of IL-1β, IL-6, IL-8, and TNF-α, especially IL-8, were significantly decreased in the sodium nitrate treatment group." (PMID 40110129, 2025). "Additionally, VCAM-1 expression on EC surface can be significantly enhanced by TNF, IL-1β, and IFNγ during atherosclerosis." (PMID 40454002, 2025). "Macrophages contribute to intimal thickening, extracellular matrix remodeling, and fibrous cap formation through IL‐1β‐mediated interaction with VSMCs in a STAT3‐dependent manner—all processes that are hallmarks of vascular remodeling during atherosclerosis progression." (PMID 40838278, 2025). "Given the established role of TRPV1–CGRP signaling within NICIs in atherosclerosis, it is plausible that IL-1β blockade might also dampen neurogenic inflammation in vascular lesions." (PMID 40977707, 2025). "Relevant animal experiments have shown that atherosclerosis-susceptible mice lacking IL-1β have reduced atherosclerotic plaque load, whereas mice exposed to excess IL-1β have increased plaque load." (PMID 41471131, 2025). "ZL, in combination with atorvastatin, can inhibit the activation of the NF-κB/NLRP3 signaling pathway and limit the release of p-NF-κB, NLRP3, caspase-1, IL-1β, and IL-18, thereby alleviating vascular inflammation and significantly attenuating atherosclerosis in rabbits." (PMID 40373162, 2025). "Deficiency of each of the three inflammasome proteins (NLRP3, ASC, Caspase 1) has been shown to reduce atherosclerotic lesion or plaque size, and the inflammasome regulates the production and recruitment of monocytes through IL-1β in the early stages of atherosclerosis." (PMID 40956333, 2025). "In addition, nicotine induces theproduction of inflammatory cytokines including interleukin (IL)-1β andIL-18 in human aortic endothelial cells, prompting vascular inflammation,another key mechanism of atherosclerosis." (PMID 40160599, 2025). "Notably, insulin resistance, T2D, NAFLD, atherosclerosis, and cardiovascular diseases, each of which are driven in part by IL-1β, are tightly interconnected." (PMID 41087719, 2025). "In addition, the CANTOS trial revealed that suppression of inflammation by canakinumab, the IL-1β antibody, resulted in a 15% reduction of cardiovascular end points in patients with established atherosclerosis." (PMID 39446306, 2025). "We identified three candidate biomarkers for T2DM-related atherosclerosis—IL1B, MMP9, and P2RY13." (PMID 41516018, 2025). "OGG1 deficiency has been shown to cause a significant increase in oxidized mitochondrial DNA (mtDNA), which, in turn, has been linked to the activation of the NLRP3 inflammasome, the secretion of interleukin-1 beta (IL-1β), and the acceleration of atherosclerosis." (PMID 40867876, 2025). "Most of the proposed interventions are expected to cause direct or indirect inhibition of the nucleotide‐binding domain leucine‐rich repeat and pyrin domain containing receptor 3 (NLRP3)‐IL‐1β/‐IL‐6 axis, because there is strong evidence for its involvement in atherosclerosis." (PMID 41182006, 2025). "Moreover, IL-1β enhances the production of other pro-inflammatory cytokines, amplifying the inflammatory response and further driving atherosclerosis." (PMID 39057626, 2024). "Vascular inflammation is known to cause atherosclerosis, so we investigated the impact of GV1001 on the development of vascular inflammation by determining the levels of the major proinflammatory cytokines, such as IL-1β, TNF-α, and IL-6." (PMID 38892314, 2024). "For example, mRNA vaccines might be created to inhibit the synthesis of IL-1β or IL-6, two cytokines that are essential for both systemic and local inflammation in atherosclerosis." (PMID 39712846, 2024).
atherosclerosis (continued). "The serum levels of IL-6, TNF-α and IL-1β were increased in atherosclerosis group." (PMID 38424494, 2024). "We proposed that the NETs, ASC, Caspase-1, IL-1β pathway is an important regulator of post-stroke inflammation which might exacerbate atherosclerosis." (PMID 39737165, 2024). "Our in vivo data of proteomics and immunostaining showed that, compared with WT group, MerTK-/- aggravates atherosclerosis in d-flow areas through upregulation of endothelial dysfunction markers (e.g. IL-1β, NF-κB, TLR4, MAPK signaling, vWF, VCAM-1 and p22phox) and mitochondrial dysfunction." (PMID 38646649, 2024). "Finally, because macrophage autophagy promotes the clearance of the NLRP3 inflammasome to limit the production of pro-inflammatory interleukin (IL)-1β in atherosclerosis, we next sought to quantify plaque IL-1β levels in our study groups." (PMID 38433753, 2024). "In the case of atherosclerosis, IL-1β promotes the exacerbation of established atherogenesis." (PMID 39232217, 2024). "In summary, our research results suggest that FMN can inhibit macrophage polarization toward the M1 phenotype (iNOS), suppress the release of proinflammatory factors, such as IL-1β, and promote M2-type polarization, thereby reducing inflammation and alleviating atherosclerosis." (PMID 38388385, 2024). "In addition, animal experiments in mice have found that the role of the NLRP3 inflammasome in atherosclerosis is due to its effector cytokine IL-1β." (PMID 38317229, 2024). "However, thus far only agents targeting the IL-1β—IL-6 pathway have shown some efficacy in atherosclerosis." (PMID 38993522, 2024). "The goals of the present study were to assess atherogenesis in a hyperlipidemic, LAB model of Jak2VF, then to define the mechanisms of accelerated atherosclerosis, especially those involving IL-1β–mediated crosstalk from mutant to WT myeloid cells that led to reduced levels of MERTK and TREM2." (PMID 39531316, 2024). "Moreover, USP20 alleviates inflammation in SMCs in TNF and IL-1β-induced atherosclerosis by deubiquitinating RIPK1, a vital factor of inflammation and cell death." (PMID 38322269, 2024). "In addition to employing circulating immune cell phenotyping to assess inflammation in atherosclerosis, levels of the pro-inflammatory cytokine IL-1β can be used as a local marker of inflammation." (PMID 38433753, 2024). "Moreover, the NLRP3 inflammasome, a complex comprising the NLRP3 receptor, ASC adapter, and pro-caspase-1, plays a pivotal role in atherosclerosis development by catalyzing the maturation of caspase-1, which in turn generates IL-1β/IL-18 from pro-IL-1β/IL-18." (PMID 38919547, 2024). "Inflammatory macrophages highly express the inflammatory chemokines Ccl2-4 and Cxcl2 and are also enriched in a large number of classical pro-inflammatory transcripts, such as Il1α, Il1β, and Nlrp3, which play an important role in regulating the progression of atherosclerosis." (PMID 39399488, 2024). "Indeed, Rac1 has been demonstrated to be a major regulatory determinant of macrophage IL-1β, which in turn is a key mechanism in promoting atherosclerosis calcification." (PMID 39596469, 2024). "CD86, a biomarker of M1-type macrophages, is markedly expressed in vulnerable arterial plaques.M1-type macrophages release ROS and pro-inflammatory cytokines, such as TNF-α, IL-1β, IL-6, and IL-12, which damage endothelial cells and blood vessels and promote atherosclerosis." (PMID 38382092, 2024). "While IL-1β has been well established to promote atherosclerosis, END1 and SELE are markers for endothelial dysfunction and may also contribute to the development of CVD." (PMID 39253968, 2024).
atherosclerosis (continued). "IL-6 is an effector cytokine downstream of IL-1β, playing a significant role in atherosclerosis." (PMID 38993522, 2024). "Furthermore, IL-1β represents an inflammatory cytokine secreted by M1 macrophages and is involved in the progression of atherosclerosis." (PMID 38388385, 2024). "IL‐1β has different effects on different types of cells involved in atherosclerosis." (PMID 36633253, 2023). "IL-1β is an important inflammatory cytokine involved in the development of inflammation, and participates in the occurrence of various inflammatory diseases such as atherosclerosis, type II diabetes, and various autoimmune diseases." (PMID 37056763, 2023). "The Canakinumab Anti-Inflammatory Thrombosis Outcome Study trial also provided proof for the inflammation hypothesis of atherosclerosis, and IL-1β inhibition highlighted the potential of anti-inflammatory therapies to improve the clinical outcomes of CVDs." (PMID 37880698, 2023). "Therefore, strategies for blocking IL-1β through inhibitors and agonists have proved to be very beneficial for atherosclerosis-driven diseases." (PMID 36851139, 2023). "The interaction between inflammation, T2D, and CVD might be explained by the co-signaling of IL-1β and IL-6 in diabetes and atherosclerosis." (PMID 37113481, 2023). "This is mediated largely by IL-1β and, in some diseases (atherosclerosis), additionally by IL-18." (PMID 37239938, 2023). "Furthermore, Kaplan-Meier analysis demonstrated that high expression of IL1B significantly predicts ischemic events in atherosclerosis." (PMID 38268851, 2023). "The Canakinumab Anti-inflammatory Thrombosis Outcomes Study (CANTOS) trial examined whether patients treated with anti-IL1β (Canakinumab) for atherosclerosis had decreased incidence of cancer." (PMID 37461742, 2023). "Chemotactic factor (Mcp-1) and inflammatory cytokines (Tnf-α, Il-1β, and Il-6) are released during the initial stage of atherosclerosis, where they trigger the infiltration of monocytes across the endothelium and promote the formation of atherosclerotic plaques." (PMID 37836404, 2023). "Both IL-1β and IL-18 play crucial roles in the development of atherosclerosis." (PMID 37374202, 2023). "Compared with young people, the elderly have significantly increased plasma inflammatory markers associated with vascular diseases such as atherosclerosis, including TNF-α, interleukin-1β (IL-1β), interleukin-6 (IL-6), C-reactive protein (CRP), interferon γ (IFN-γ), MCP-1, and MMPs." (PMID 37894840, 2023). "Both IL-1β and IL-18 exert pro-inflammatory effects through the nuclear factor kappa-light-chain-enhancer of activated β cells (NF-κβ) pathway and are involved in the atherosclerosis process." (PMID 36753488, 2023). "IL-1β is an important regulator in inflammatory immune responses and plays an essential role in a wide range of diseases, such as cancer, rheumatoid arthritis, and atherosclerosis." (PMID 37079558, 2023). "Therefore, drugs targeting IL-1β have demonstrated improved clinical outcomes in cardiovascular disease, including atherosclerosis, myocardial infarction and pericarditis." (PMID 37336361, 2023). "Our results indicate the most important cytokines identifying obstructive CAD are IL-1β, which was indeed chosen as the target of the first anti-inflammatory trial to treat atherosclerosis and IL-12, that drives the CD4 + Th1 response, which is pro-atherogenic." (PMID 37004526, 2023). "Ample evidence has been reported to show the important role that IL‐1β plays in atherosclerosis." (PMID 36633253, 2023). "In addition, hydroxytyrosol, a major phenolic compound in extra-virgin olive oil, can positively control atherosclerosis by protecting IL-1β-induced endothelial cells, suggesting that regulation of the EndMT process plays a major role." (PMID 37237925, 2023).
atherosclerosis (continued). "Moreover, IL-1β antibody treatment decreases plaque stability indices in Apoe−/− mice with advanced atherosclerosis, indicating an unexpected role of IL-1β in regulating fibrous cap formation." (PMID 36782020, 2023). "It is therefore noteworthy that we could document here significantly higher IL-1β plasma concentrations in T2DM patients with advanced atherosclerosis." (PMID 37710315, 2023). "In contrast, increase IL-1β expression might accelerate the production of atherosclerotic inflammatory factors and the progression of atherosclerosis." (PMID 36791122, 2023). "In addition, oxidized LDL activates transcription of NLRP3 and pro-IL-1β, promoting atherosclerosis." (PMID 38068879, 2023). "Curiously, inhibition of IL1B in murine atherosclerosis inhibited cap formation." (PMID 37671141, 2023). "IL-1β is a pro-inflammatory cytokine that not only facilitates the inflammatory responses in the aorta and influences the proliferation of vascular smooth muscle cells, but also participates in vascular endothelial dysfunction and facilitates atherosclerosis." (PMID 37895334, 2023). "Interleukins (IL-1β and IL-6), chemokines, interferon-γ (IFN-γ), and tumor necrosis factor-alpha (TNF-α) are the cytokines commonly associated with endothelial dysfunction, vascular inflammation, and atherosclerosis." (PMID 37629526, 2023). "The IL-1β/IL-6 axis is an important signaling pathway for human and murine atherosclerosis." (PMID 36178662, 2023). "Peter Libby and his collaborators focused on the potential value of using IL-1β as a treatment target for atherosclerosis, including performing biomarker-directed application of an anti-inflammatory strategy and personalized allocation of therapy for cardiovascular patients." (PMID 37123477, 2023). "Aside from IL-1β, IL-1α plays an equally important role in atherosclerosis." (PMID 37446157, 2023). "This is significant because NLRP3 may contribute to the pathogenesis of atherosclerosis through a signalling pathway that triggers PCSK9 secretion via IL-1β stimulation." (PMID 38143759, 2023). "Moreover, the CANTOS trial, for the first time, showed that inhibition of inflammation using an antibody against Il-1β decreased cardiovascular events, providing further evidence for the importance of inflammation in atherosclerosis." (PMID 37396595, 2023). "Notably, patients with RA are at an increased risk of premature death due to accelerated atherosclerosis in cardiovascular comorbidities, while NLRP3 inflammasome activation and production of IL-1β, TNF-α, and IL-6 are also key immune mediators of RA." (PMID 37720032, 2023). "Studies reported that IL-1β plays multiple roles in the interaction among inflammatory cells, smooth muscle cells, vascular endothelial cells, and extracellular matrix within the atheromatous plaque in all stages of atherosclerosis." (PMID 36791122, 2023). "Enhanced secretion of IL-1β correlates with increased secretion of reactive oxygen species (ROS), thus connecting inflammation with oxidative stress, and finally resulting in accelerated atherosclerosis and vascular damage." (PMID 36835838, 2023). "Higher production of IL-1β might be involved, at least in part, in the acceleration of atherosclerosis in Apoe-/-Card9-/- mice and might be due to increased CD36 expression." (PMID 37528097, 2023). "Anti-inflammatory therapies, such as IL1B antagonism and colchicine, reduce the incidence of clinical events in patients with advanced atherosclerosis, but whether this is achieved partly by increasing cap thickness is also unknown." (PMID 37671141, 2023). "Global targeting of IL-1β demonstrated a decrease in atherosclerosis burden in mice." (PMID 37539090, 2023). "We then detected the levels of IL-1β and IL-18 in arteries with atherosclerosis." (PMID 37198205, 2023).
atherosclerosis (continued). "Type 2 diabetes mellitus may also play an important role in the pro-inflammatory milieu of atherosclerosis, as shown by the increased IL-1β mRNA in atherosclerotic plaques of patients with type 2 diabetes compared to non-diabetic plaques." (PMID 36555579, 2022). "Besides CANTOS, another trial enrolling 189 volunteers also explored the feasibility of blocking IL-1β in treatment of atherosclerosis." (PMID 36204568, 2022). "IL-1β is a powerful mediator of atherosclerosis development." (PMID 35328023, 2022). "Additionally, we observed an increase in the secretion of progressive atherosclerosis cytokines, such as IL-6, IL-1β, and TNF-α, in the ox-LDL treated HUVEC supernatants." (PMID 35137664, 2022). "IL-1β and IL-18 involve both innate and adaptive immune responses, performing a significant role in inflammatory development of atherosclerosis, cardiomyopathy, abdominal aortic aneurysm, calcific aortic valve disease, heart failure, and cardiovascular and cerebrovascular ischemic injury." (PMID 36204568, 2022). "However, high levels of TNFα and IL-1β in patients with atherosclerosis have been shown to decrease the expression of KLB." (PMID 36006939, 2022). "IL-1β is known to be produced by hematopoietic cells, as well as vascular endothelial and smooth muscle cells under inflammatory conditions, in which they also induce proliferation and have inflammatory effects contributing to the process of atherosclerosis." (PMID 35204152, 2022). "Notably, intracellular protein NACHT, LRR, and PYD domain-containing protein 3 (NLRP3) form the NLRP3 inflammasome, which mediates the effects of IL-1β related to atherosclerosis." (PMID 35563294, 2022). "Mechanistically, this study further elucidated the crosstalk between lipids and inflammation remaining in macrophages, in which the NLRP3 inflammasome and its downstream IL-1β act as executors to initiate the inflammatory response that ultimately leads to atherosclerosis." (PMID 35864109, 2022). "Inflammatory cytokines such as IL-1β are involved in atherosclerosis progression." (PMID 35566578, 2022). "Indeed, the deleterious effect of TET2 knockdown can be reversed by treatment with the NLRP3 inhibitor MCC950, indicating the pivotal role of IL-1β/NLRP3 inflammasome in TET2 atherosclerosis-related signaling." (PMID 35663390, 2022). "The phagocytosis of oxLDL induces the expression of pro-IL-1β and ROS by the cathepsin B pathway, resulting in activation of the NLRP3 inflammasome, inducing macrophages to secrete IL-1β, and promoting macrophage transfer into foam cells during atherosclerosis." (PMID 36082127, 2022). "Therapeutic strategies directly targeting proinflammatory cytokines [e.g. tumor necrosis factor-alpha (TNF-α), interleukin-1-beta (IL-1β) neutralization, methotrexate and colchicine] have shown great promise in experimental and clinical studies in atherosclerosis." (PMID 35758143, 2022). "Excessive ox-LDL in the body can trigger an inflammatory response, activate macrophages, and up-regulate the expressions of pro-inflammation cytokines (such as IL-1β and TNF-α), which ultimately causes endothelial cell damage and atherosclerosis plaque formation." (PMID 36557935, 2022). "Previous studies have demonstrated that ROS can activate NLRP3 inflammasomes and then cause cellular damage by inducing caspase-1 activation and IL-1β secretion in the development of atherosclerosis, and IL-1β has been noted as the most important pro-inflammatory cytokine in IVD degeneration." (PMID 35887297, 2022). "IL-1β and IL-18 have important roles in the pathogenesis of atherosclerosis." (PMID 36589841, 2022).